NRP1 (neuropilin 1)
Diseases named in the same sentence as NRP1 in open-access papers (continued):
Sharing a sentence is not in itself a finding about the gene and the disease.
infection (continued). "What emerges is a complex role for Nrp1 in the CD8 T cell response, which is dependent upon both the timing of Nrp1 expression during the primary versus secondary response and the nature of the infection." (PMID 31118303, 2019). "When deleted prior to infection, the absence of Nrp1 reduced the size of the recall response, indicating Nrp1 promotes the ability of memory cells to expand upon antigen reexposure." (PMID 31118303, 2019). "Nrp1 expression was low in both cases during the early stages of infection (day 7 [d7]), but were significantly upregulated on d14, when CD8 T cell responses peak in MHV-68 infection." (PMID 31118303, 2019). "In summary, an rVSV engineered to express HTLV-1 primary receptor, especially human NRP1, may represent a drug candidate that has potential for the development of unique virotherapy against HTLV-1 de novo infection." (PMID 29212930, 2018). "Infection of RAoSMC with Ad.NRP1 WT did not significantly alter the migration of RAoSMC towards a gradient of PDGF-BB, compared with control cells infected with Ad.LacZ." (PMID 26410366, 2015). "Furthermore, these authors found that ACE2-expressing NRP1-KO cells contained fewer RNA transcripts than the ACE2-KO NRP1-expressing cells, while the double-KO cells exhibited little to no infection." (PMID 39205219, 2024). "We found that PNS sensory and autonomic neurons, supporting glial cells, and spinal cord neurons are susceptible and, in most cases, permissive to productive infection with SARS-CoV-2 via direct neural invasion, independent of hACE2, using NRP-1 as an entry factor." (PMID 39125815, 2024). "This could explain recent findings in HMC3 expressing relevant receptors i.e., ACE2, TMPRSS2, CD147, and NRP1, where no productive infection by some strains of SARS-CoV-2, but to Wuhan, Delta, and Omicron was reported." (PMID 39881814, 2024). "In addition, we detected elevated frequencies of Nrp-1-expressing CD8+CD11a+ antigen-experienced T cells in the brain compared to CD8+CD11a+ T cells in the spleen and blood of PbA-infected mice at 6 days post infection." (PMID 38019895, 2023). "Thus, Neuropilin-1 (NRP1) appears to trigger SARS-CoV-2 viral entry and infection." (PMID 36507266, 2022). "Interestingly, these effects were only observed with a persistent strain of MHV-68, but Nrp1 did not appear to affect recall responses in infection with a nonpersistent strain of the virus." (PMID 31118303, 2019). "This suggests that viral capture is inversely correlated to productive infection, and could be independent of NRP-1 and/or DC-SIGN expression level." (PMID 28426803, 2017). "Therefore, the low abundance of ACE2 in the cerebellar sections may explain the non-productive infection observed here, but the expression of Nrp1 and Bsg does not fully account for the permissiveness of glial cells." (PMID 35746689, 2022). "The resistance of trophoblast cells to MCMV infection correlated with the absence of neuropilin-1 (NRP1), a cellular receptor required for efficient infection of several cell types." (PMID 41288331, 2025). "They found that NRP-1 expression alone did not promote infection; however, when co-expressed with ACE-2 and transmembrane protease serine 2, infection of HEK-293T cells was significantly enhanced." (PMID 40008234, 2024). "There are possibilities that other receptor candidates, such as CD147, AXL and NRP1, do not contribute to SARS-CoV-2 infection in iPSC-BMELCs, as their inhibitors had little inhibitory effect on the infection." (PMID 38584257, 2024). "The study concluded that although NRP1 did not promote infection itself, its coexpression with ACE2 and TMPRSS2 enhanced infection." (PMID 38887342, 2024). "siRNAs specific for NRP1, but not AXL, strongly inhibited the infection of astrocytes by SARS-CoV-2, as assessed by the reduced expression of viral nucleocapsid (N) mRNA." (PMID 36314791, 2022).
infection (continued). "The authors observed that NRP-1 only with the coexpression of ACE-2 and/or TMPRSS2 enhanced infection of coronavirus, as opposed to NRP-1 alone." (PMID 34202613, 2021). "Although NRP1 did not promote infection in HEK-293T cells, its coexpression with ACE2 and TMPRSS2 markedly enhanced infection." (PMID 33082293, 2020). "Interestingly, lapatinib had a similar effect, most prominently at 30 minutes after infection, on the surface level of ACE2, but not NRP1." (PMID 37581931, 2023). "It was further found that in HEK293T cells with almost no endogenous expression of ACE2 and NRP1, overexpression of NRP1 did not affect the infection degree of SARS-CoV-2 pseudovirus, but coexpression of NRP1, ACE2 and TMPRSS2 significantly promoted viral entry and infection." (PMID 37645223, 2023). "Consequently, the treatment of cells with VPA before infection impairs production of SARS-CoV-2 infectious viruses, but not that of other ACE2- and NRP1-independent viruses (VSV and HCoV-229E)." (PMID 34635175, 2021). "Nrp1 is upregulated with both persistent and nonpersistent MHV-68 infections." (PMID 31118303, 2019). "To understand the role of Nrp1 on CD8 T cells upon MHV-68 infection, we initially measured the kinetics of Nrp1 expression on CD8 T cells after either persistent (FS73R) or nonpersistent (FS73) MHV-68 infection." (PMID 31118303, 2019). "Recent studies have highlighted that alternate receptors may be used for SARS-CoV-2 entry to the cells of the CNS, with neuropilin-1, CD147 and DPP4 reported as potential SARS-CoV-2 entry factors for astrocytes, and that TMPRSS2 is not required for infection of neurons." (PMID 38995681, 2024). "The same principle of reducing infection without impacting function should be applied not only to host receptors such as ACE2, but also other cofactors such as NRP1 because a proper level of NRP1 protein is essential for cardiovascular and neuronal development." (PMID 37560522, 2023). "This suggests that the S protein may exploit additional receptors for infection, such as the innate immune system, including C-lectin type receptors (CLR), toll-like receptors (TLR) and neuropilin-1 (NRP1), and the non-immune receptor glucose regulated protein 78 (GRP78)." (PMID 34360529, 2021).
kidney disease (9 papers, 2019 to 2024). "Previously, NRP-1 has been associated with liver pathologies and kidney disease." (PMID 38791476, 2024). "In conclusion, our study highlights the significant involvement of Nrp1 in the advancement of renal diseases." (PMID 38977708, 2024). "Our findings provide insights into a potential therapeutic approach for improving kidney disease by targeting NRP1." (PMID 38977708, 2024). "We also found that Nrp1 is involved in the progression of renal disease by activating TGF-β-dependent and -independent Smad 2/3 signaling in distal renal tubular epithelial cells (TECs)." (PMID 38977708, 2024). "The study showed a positive correlation between NRP-1 levels and the clinic-pathological parameters of renal disease." (PMID 31533337, 2019). "NRP-1 deposits were also increased in the glomeruli of patients with active renal disease when compared with normal kidneys and correlated with urinary NRP-1 levels." (PMID 31533337, 2019). "Similarly, a study by Schrameck and colleagues explored the expression of NRPs in fibrotic kidney disease and showed that TGFβ1 downregulates the expression of NRP1 in fibrotic renal tissues." (PMID 38646784, 2024). "Together, these findings suggest that Nrp1 plays multiple pro-fibrotic roles in kidney diseases." (PMID 38977708, 2024). "It is worth noting that the role of NRP-1 has also been confirmed in kidney diseases via elevated vascular permeability and endothelial cell apoptosis leading to imbalanced kidney regulations also increasing renal disorders." (PMID 34209289, 2021). "The interaction of Nrp1 with TGF-β and TNF-α suggests its potential involvement in acute injury and the chronic progression of kidney disease." (PMID 38977708, 2024). "NRP-1 urinary levels could discriminate active renal disease from non-active disease with a sensitivity and specificity of 73.33% and 97.5%, respectively, suggesting that its measurement is useful in diagnosis and a reliable marker of renal disease activity in patients with SLE." (PMID 31533337, 2019).
neurodegenerative disease (6 papers, 2016 to 2025). A disorder of the central nervous system characterized by gradual and progressive loss of neural tissue and neurologic function. "In patients with this neurodegenerative disease, there is a significant decrease in the level of neuropilin-1 (69.94 vs. 167.28, p < 0.00001)." (PMID 37959320, 2023).
cardiovascular disease (5 papers, 2021 to 2023). "Ingenuity pathway analysis demonstrated alterations in several pathways in BM ECs in response to anti-NRP1, including organismal survival, hematological system development and function, hematopoiesis, cardiovascular disease and hematologic disease pathways." (PMID 34848712, 2021).
hematologic disease (4 papers, 2021 to 2025). "In summary, our study is the first assessment of the positive rate and diagnostic efficacy of NRP‐1/CD304 in various common hematological diseases with large samples." (PMID 36965095, 2023). "Evaluation of diagnostic efficacy of NRP‐1/CD304 in three hematological diseases with positive expression." (PMID 36965095, 2023). "The study was to evaluate the diagnostic efficacy of NRP‐1/CD304 in hematological diseases." (PMID 36965095, 2023). "Bone marrow samples from 297 newly diagnosed patients with various hematological diseases were collected to detect the expression of NRP‐1/CD304 by flow cytometry (FCM)." (PMID 36965095, 2023). "Age, quantity distribution, and the positive rate of NRP‐1/CD304 in 297 patients with different types of hematological diseases." (PMID 36965095, 2023). "The purpose of this study was to investigate the expression of NRP‐1/CD304 in BPDCN and other common hematological diseases, and to systematically evaluate its diagnostic efficacy, thus to guide the panel design of flow immunophenotyping in diagnosis and MRD of various hematological diseases." (PMID 36965095, 2023). "This indicates that NRP‐1/CD304 has no obvious diagnostic and follow‐up study value in hematological diseases other than BPDCN, B‐ALL and AML." (PMID 36965095, 2023). "Our study clarifies the application value of NRP‐1/CD304 in flow immunophenotypic diagnosis and MRD detection of various hematological diseases." (PMID 36965095, 2023). "Except for BPDCN, AML, and B‐ALL, NRP‐1/CD304 does not need to be included in the flow detection protocol of other hematological diseases." (PMID 36965095, 2023). "We found that NRP‐1/CD304 was only expressed in BPDCN, B‐ALL and AML, but not in other common hematological diseases." (PMID 36965095, 2023). "NRP‐1/CD304 is only expressed in BPDCN, B‐ALL and AML, but not in other common hematological diseases." (PMID 36965095, 2023).
infectious disease (4 papers, 2015 to 2023). A disorder directly resulting from the presence and activity of a microbial, viral, or parasitic agent in humans. "Of particular interest will be the investigation of Nrp-1 on CD8+ T cell responses during these infectious diseases to understand the general impact of Nrp-1." (PMID 38019895, 2023).
adenocarcinoma (3 papers, 2016 to 2022). A common cancer characterized by the presence of malignant glandular cells. "For this purpose, prostate (PC3) and breast (MDA-MB-231) adenocarcinoma cells were used as models since they express a significant level of endogenous neuropilin-1 and are known to respond to activation of neuropilin-1-dependent pathways." (PMID 27798666, 2016). "Treatment with EG00229, an inhibitor of neuropilin 1 (NRP1) binding to VEGF, radio-sensitized adenocarcinoma cell lines and reduced N-cadherin and vimentin, while NRP1 overexpression increased them." (PMID 36230484, 2022). "Moreover, mRNA expression VEGFD, FGF2 MMP2, NRP1 and NRP2 was decreased in lepidic adenocarcinomas when compared to the normal lungs." (PMID 29137669, 2017). "Interestingly, mRNA expression of the MMP2, NRP1 and NRP2 genes was lower (but not significant) in lepidic-type adenocarcinomas as compared to normal tissues from the same patients." (PMID 29137669, 2017).
metabolic disease (3 papers, 2021 to 2025). A congenital disorder (due to inherited enzyme abnormality) or acquired (due to failure of a metabolically important organ) disorder resulting from an abnormal metabolic process. "Future studies should explore isoform-specific mechanisms, post-translational modifications, the control mechanisms of the NRP1/2 molecular switch, and the broader implications of NRPs in immune and metabolic disorders." (PMID 40134439, 2025). "NRP-1 serves as a co-receptor to several growth factor (GF) receptors, including vascular endothelial, the hepatocyte and the platelet-derived GF (VEGF, HGF, PDGF, respectively) receptors, all of which are potentially involved in metabolic diseases." (PMID 38638882, 2024).
neurological disorders (3 papers, 2022 to 2024). "NRP1, a membrane-bound protein crucial for neurodevelopment, and contributing to neurological diseases like neuropathic pain and ischemic brain injury, was downregulated." (PMID 39330583, 2024). "Therefore, SARS-CoV-2 through NRP-1 in the olfactory epithelium of the nasal cavity may transmit to the brain leading to different neurological disorders including headache, confusion, hallucination, and convulsion." (PMID 36009579, 2022).
gastrointestinal tumor (2 papers, 2022 to 2024). "We therefore characterized the expression profiles of a number of genes involved in SARS-CoV-2 infection pathway and found higher ACE2, TMPRSS2, TMPRSS4, SCARB1, CTSL and NRP1 expression in all GI tumor samples relative to their normal counterparts." (PMID 35970857, 2022).
peripheral neuropathy (2 papers, 2016 to 2020). A disorder affecting the peripheral nervous system. "We made an interesting observation that the peripheral neuropathy caused by HFD was strongly associated with the decrease in the expression of Sema3a, Neuropilin 1, Plexin A, and A2AR in the spinal cord." (PMID 32566683, 2020). "CMT‐GlyRS mutants competed with VEGF‐A for binding to Nrp1, and heterozygosity for Nrp1 enhanced the peripheral neuropathy phenotype of GarsP278KY/+ mice." (PMID 27352040, 2016).
psychiatric disorder (2 papers, 2013 to 2024). A disorder characterized by behavioral and/or psychological abnormalities, often accompanied by physical symptoms. "Nutritional reset of HMRD with l-tryptophan and 5-HT could help resolve neuro-psychiatric disorders (resulting from viral hijack of NRP1), is of high priority in clinical management of neuro-PASC." (PMID 38555403, 2024).
retinopathy (2 papers, 2015 to 2022). "Moreover, intravitreal administration of soluble Nrp-1, which neutralizes Sema3A bioactivity, reduces microglial infiltration and pathological neovascularization in retinopathy." (PMID 35045890, 2022).
bacterial diseases (1 paper, 2017). "As NRP1 was required for defense responses against cold stress and avirulent bacteria, this suggests that NRP1 may play a role in PsCA-induced defense against chilling and bacterial diseases." (PMID 29403505, 2017).
blood cancers (1 paper, 2024). "We observed that Nfkb1 exhibited higher transcriptional activity in Nrp1 + DT cells, whereas Etv6, a transcription factor known mainly for its role in hematology and blood cancers, showed higher activity in Nrp1-DT cells." (PMID 38977708, 2024).
myopathy (1 paper, 2015). A disease of the muscle in which the muscle fibers do not function properly. "Our findings raise the possibility that loss of Nrp1 in visceral smooth muscle could potentially be an underlying contributor to myopathy leading to impaired GI motility in human CIPO, a possibility that merits future investigation." (PMID 25659123, 2015).
vasculature disorders (1 paper, 2022). "Meanwhile, by performing whole-brain clearing with PEGASOS, microvascular reconstruction, western blotting, and ELISA, we found that NRSF-shRNA markedly alleviated the vasculature disorders and rescued the suppression of NRP-1, VEGF, and VEGFR2 in the hippocampus of diabetic ischemic mice." (PMID 35645950, 2022).
NRP1 also shares sentences with these, for which no sentence is quoted: esophageal squamous cell carcinoma (6 papers); myeloma (6); immune dysfunction (5); cardiac hypertrophy (4); lupus (4); Cirrhosis (3); colorectal adenocarcinoma (3); Ewing sarcoma (3); influenza (3); viral diseases (3); adenomyosis (2); allergic asthma (2); Angiomatous Meningioma (2); Arrhythmia (2); breast invasive carcinoma (2); cardiac disease (2); contact dermatitis (2); cutaneous melanoma (2); ductal adenocarcinoma (2); ependymoma (2); gastrointestinal carcinoma (2); idiopathic pulmonary fibrosis (2); injury (2); malignant glioma (2); metabolic syndrome (2); metastatic colorectal cancer (2); multiple myeloma (2); Myocardial fibrosis (2); ovarian tumors (2); Parkinson disease (2).
A further 135 diseases each share a sentence with NRP1 in 2 papers or fewer.